SMOC2 (SPARC related modular calcium binding 2)
Diseases named in the same sentence as SMOC2 in open-access papers (continued):
Sharing a sentence is not in itself a finding about the gene and the disease.
endometriosis (1 paper, 2017). The growth of functional endometrial tissue in anatomic sites outside the uterine body. "Since real-time PCR is the gold standard for the quantification of gene expression, it is possible that SMOC2 may be related to or participate directly in the development of endometriosis." (PMID 28678915, 2017). "Additionally, the expression of ID2, PRELP and SMOC2 genes is similar between the normal endometrium and the eutopic endometrium of women with endometriosis." (PMID 28678915, 2017). "The ID2 gene expression was increased in the most advanced stage of endometriosis and in ovarian endometriomas, the PRELP was more expressed in peritoneal lesions, and the SMOC2 was highly expressed in both peritoneal and endometrioma lesions." (PMID 28678915, 2017). "In the current study, we compared the expression of the ID2, PRELP and SMOC2 genes in endometriotic lesions (ovarian and peritoneal) and in the eutopic endometrium of women with and without endometriosis in the proliferative phase of their menstrual cycle." (PMID 28678915, 2017). "The expression of the ID2, PRELP and SMOC2 genes was compared between the endometrium of women without endometriosis in the proliferative phase of their menstrual cycle and the eutopic and ectopic endometrium of women with endometriosis in the proliferative phase." (PMID 28678915, 2017).
glaucoma (1 paper, 2021). Increased pressure in the eyeball due to obstruction of the outflow of aqueous humor. "Genotyping of SNP rs13208776 (A/G), located within intron 4 of the SMOC2 gene, revealed a significantly higher frequency of GA genotype than that of the GG in glaucoma patients compared to controls." (PMID 33919241, 2021). "The primary angle-closure glaucoma (PACG) patients had a significantly higher frequency of GA genotype, thus indicating that the SMOC2 gene mutation may be a risk factor." (PMID 33919241, 2021).
head and neck squamous cell carcinoma (1 paper, 2022). A squamous cell carcinoma that arises from any of the following anatomic sites: lip and oral cavity, nasal cavity, paranasal sinuses, pharynx, larynx, and salivary glands. "Furthermore, SMOC2 expression was found to be higher in the metastatic form of head and neck squamous cell carcinoma and canine mammary adenocarcinoma when compared to their primary form." (PMID 35869056, 2022).
kidney cancer (1 paper, 2022). Primary or metastatic malignant neoplasm involving the kidney. "Collectively, such SMOC2-induced EMT events are frequently associated with the metastatic process of many epithelial tumors (e.g. kidney cancer), which involves the detachment and extravasation of cancer cells from the primary site to their migration, invasion and proliferation at distant organs." (PMID 35869056, 2022).
metabolic syndrome (1 paper, 2024). A cluster of metabolic risk factors for CARDIOVASCULAR DISEASES and TYPE 2 DIABETES MELLITUS. "Smoc2 has been reported to be involved in multiple cellular processes, including fibrosis, inflammation, cell differentiation, cell proliferation, and lipid deposition observed in metabolic syndrome." (PMID 39273278, 2024).
osteoporosis (1 paper, 2023). A condition of reduced bone mass, with decreased cortical thickness and a decrease in the number and size of the trabeculae of cancellous bone (but normal chemical composition), resulting in increased fracture incidence. "Multiple proteins that showed strong evidence to be associated with osteoporosis-related traits were supported by previous studies, such as RSPO3, IDUA, SMOC2." (PMID 37448626, 2023). "Our MR study further strengthens the positive effect of SMOC2 on multiple osteoporosis-related traits in the general population." (PMID 37448626, 2023).
periodontal disease (1 paper, 2020). "Smoc2−/− mutants exhibited alterations characteristic of chronic inflammation marking periodontal disease." (PMID 32908163, 2020).
radicular dentin dysplasia (1 paper, 2024). "Secreted modular calcium-binding protein 2 (SMOC2), an extracellular glycoprotein belonging to the secreted protein acidic and rich in cysteine (SPARC) family, has been identified as a pathogenic gene for radicular dentin dysplasia." (PMID 38612855, 2024).
small intestinal adenomas (1 paper, 2018). "This was confirmed by in situ hybridization with a probe detecting the mRNA expression of Lgr5 or Smoc2 in small intestinal adenomas of ApcMin mice." (PMID 30177706, 2018).
Stillbirth (1 paper, 2019). Death of the fetus in utero after at least 22 weeks of gestation. "We identified 12 genome-wide significant associations between these traits and genetic loci, including variants near CACNA2D3 with gestation length, MSRB3 and MSANTD1 with litter size, SMOC2 with cesarean section rate and UFM1 with stillbirth rate." (PMID 31263560, 2019).
tubular adenoma (1 paper, 2020). A usually polypoid neoplasm arising from the glandular epithelium. "On the other hand, traditional serrated adenomas (TSAs) and tubular adenomas (TAs) exhibited focal or diffuse patterns of SMOC2 expression with moderate to strong stain intensity." (PMID 32884102, 2020).
tumor (17 papers, 2015 to 2025). "SMOC2 expression was negatively associated with lymphatic invasion (P = 0.002), venous invasion (P = 0.002), and tumor stage (P < 0.001), while being positively associated with nuclear β-catenin expression (P = 0.030)." (PMID 32884102, 2020). "Remarkably SMOC2 positivity was associated with improved recurrence-free survival along with female sex, tumor size, and the N stage." (PMID 32184420, 2020). "SMOC2 is a protein that is secreted into the matrix and plays a role in several pathophysiological processes, including angiogenesis, tumor development, tissue fibrosis, and calcification, and can also serve as a predictive biomarker for various diseases." (PMID 40297163, 2025). "Both the downregulation of SMOC2 stemness gene and the upregulation of enterocytic differentiation genes indicated that tumor organoids were sensitive to BMP4 action (BMP4 and B + D media), while DBZ treatment failed to induce any mucosecretory gene." (PMID 38684650, 2024). "Studies have shown that targeting the tumor stem cell marker gene SMOC2 can inhibit the proliferation of endometrial cancer cells and overcome chemoresistance." (PMID 34976169, 2022). "The sh-circ007428+inhibitor group or sh-circ007428+SMOC2 group showed a decrease in sensitivity to gemcitabine and an increase in tumor volume and weight." (PMID 34976169, 2022). "In recent years, SMOC2 has been reported to be highly expressed in tumor tissues and to promote tumor migration, invasion and growth." (PMID 36513634, 2022). "Collectively, the results from our in vivo IR xenograph mouse models provide evidence that SMOC2 promotes RCC tumor cell growth as well as metastasis to the lungs." (PMID 35869056, 2022). "As displayed by the GEPIA database, the levels of SMOC2 were markedly higher in 179 PDAC tumor tissues than in 171 normal samples." (PMID 35662010, 2022). "We provide evidence here of a reduction in tumor stemness characteristics as seen by reduced Lgr5 and Smoc2 in both CAC and Apcmin/+ models, as well as in tumor organoids derived from both models." (PMID 34710062, 2021). "SMOC2 was involved in multiple biological processes, including cell cycle progression, cell attachment, and tumor development." (PMID 34869577, 2021). "In vitro studies also demonstrated that induced SMOC2 expression in DLD1 cells exerts a suppressive role in tumor growth as well as in migration, colony, and sphere formation abilities." (PMID 32884102, 2020). "On the other hand, there are a few reports suggesting a tumor suppressive role for SMOC2 in some cancers." (PMID 32184420, 2020). "In one case of LGD, Smoc2 appeared to be limited to tumor bases, but Lgr5 and Ascl2 showed diffuse and patchy distribution." (PMID 28747693, 2017). "Strikingly, oral treatment with STmΔaroA/ΔansB negated this intrinsic tumour control, as evidenced by expression of Lgr5, Smoc2, and Vim, to levels comparable to the PBS control group, in contrast to the STmΔaroA treatment, which reduces expression of these genes." (PMID 39558103, 2024). "Finally, we translated our findings in vivo through various xenograph models showing SMOC2 promoting tumor growth and metastasis." (PMID 35869056, 2022). "Given the in vitro impact that SMOC2 has on RCC survival and the characteristics of EMT, we next determined whether SMOC2 impacts RCC tumor growth and metastasis in vivo." (PMID 35869056, 2022). "Western blot analysis revealed SMOC2 protein expression in tumor tissue." (PMID 34976169, 2022). "Therefore, further studies are required to reveal the functional significance of SMOC2 expression in each cancer type and, in particular, to confirm our results of tumor suppressive roles in CRCs." (PMID 32884102, 2020). "Taken together, our results suggest SMOC2 as a candidate tumor suppressor in CRC progression." (PMID 32884102, 2020).
tumor (continued). "Considering the established oncogenic roles of CEACAM5, it is reasonable to speculate that SMOC2-induced CEACAM5 down-regulation may contribute to a tumor suppressive role of SMOC2 in CRC progression." (PMID 32884102, 2020). "Furthermore, multivariate analysis revealed that SMOC2 was an independent prognostic marker (HR = 0.555, P = 0.006) along with perineural invasion (HR = 1.890, P < 0.001), tumor stage (HR = 3.029, P < 0.001), and adjuvant chemotherapy (HR = 0.281, P < 0.001)." (PMID 32884102, 2020). "To examine whether the tumor suppressive functions of SMOC2 are mediated through the secreted SMOC2 protein in an extracellular space, we treated DLD1 with recombinant human SMOC2 protein." (PMID 32884102, 2020). "However, considering that SMOC2 expression is substantially higher in precancerous colorectal lesions such as TSAs and TAs, it is less likely that SMOC2 exerts its tumor suppressive function at the early stage of tumor development." (PMID 32884102, 2020). "Taken together, our results suggest that SMOC2 may act as a tumor suppressor in CRC progression." (PMID 32884102, 2020). "The proliferation and metastatic potential of SMOC2 overexpressing ACHN and 786-O cell lines were validated in vivo by their significantly higher tumor growth in kidneys and systemic dissemination into other organs when compared to their respective controls." (PMID 35869056, 2022). "Meanwhile expression of gene DPT, SMOC2, GLP2R, FBLN5 and LMOD1 were down-regulated in tumor tissues." (PMID 25970782, 2015). "Compared with that in the sh-circ0074298 group, the expression of hsa_circ_0074298 and miR-519d in tumor tissues in the sh-circ0074298+SMOC2 group was not significantly different." (PMID 34976169, 2022). "In total, 28% of 591 CRCs were positive for SMOC2, but SMOC2 positivity had negative correlations with lymphatic invasion (P = 0.002), venous invasion (P = 0.002), and tumor stage (P < 0.001)." (PMID 32884102, 2020). "The level of SMOC2 in 78 tumor samples was markedly higher than in pair-matched nontumor tissues." (PMID 35662010, 2022). "We assume that similar to SMOC2, SMOC1 might also be involved in tumor development." (PMID 34869577, 2021).
cancer (15 papers, 2019 to 2025). A tumor composed of atypical neoplastic, often pleomorphic cells that invade other tissues. "Frequency of CD44+ cells and expression levels of Cd44 and other cancer stem cell markers Ascl2, Lgr5 and Smoc2 were markedly reduced in Mex3a-deficient tumors." (PMID 36276637, 2022). "We further investigated how SCNA influences gene expression and found the expression of FCN3, FREM1, MNS1, and SMOC2 was significantly positively associated with SCNA in most cancers, which indicated that aberrant SCNA of a gene might contribute to the progression of various cancers." (PMID 40297163, 2025). "SMOC2 was also identified to exert a regulatory function on various cancers and diseases, including pancreatic cancer." (PMID 35662010, 2022). "The apparent role of SMOC2 in tissue development and remodeling correlates with its effects in cancer progression." (PMID 35869056, 2022). "Over recent years, SPARC member SMOC2 was studied for its role in development and fibrosis, suggesting a possible function for this protein in cancer progression since these tissue-altering processes share key signaling pathways." (PMID 35869056, 2022). "Recently, an MCP called SPARC-Related Modular Calcium-Binding (SMOC2) has been identified for its emerging roles in cancers, yet its contribution in RCC remains elusive." (PMID 35869056, 2022). "In CRC, SMOC2 has been suggested as a prognostic marker, having tumor suppressor activity in cancer progression." (PMID 34827720, 2021). "According to previous reports on cancer cell lines, the biological functions of SMOC2 are mostly related to pro-oncogenic properties." (PMID 32184420, 2020). "We observed a significantly attenuated proliferation profile in cancer cells that were transfected with SMOC2, compared to those transfected with a control plasmid." (PMID 32884102, 2020). "Further, the FLNA editing state influenced genes associated with proliferation, cancer, and stress response, with some being upregulated in FLNAR (e.g., Naca, Myof, Smoc2, and Hprt) and others being upregulated in FLNAQ ECs, like the AP-1 transcription factor complex (Atf3, Fos, and Jun)." (PMID 40471139, 2025). "Our study reveals a previously unrecognized role for SMOC2 in cancer progression by upregulating EMT features of RCC cells through integrin pathways and suggests that such regulation of cellular phenotype can lead to an increase in mitogenic and migratory behavior." (PMID 35869056, 2022). "Notably, SMOC2 expression further decreased in the metastatic cancer cells in the lymph nodes compared to primary PTC, suggesting a functional implication of SMOC2 down-regulation in the metastatic progression of PTC." (PMID 32184420, 2020). "Notably, SMOC2 expression was significantly reduced in the cancer cells at invasive fronts (n = 89)." (PMID 32884102, 2020). "Furthermore, the functional significance of SMOC2 on cancer growth and migration were also explored using CRC cell lines." (PMID 32884102, 2020). "However, there are only a few studies on the functional or prognostic significance of SMOC2 in human cancers." (PMID 32184420, 2020). "Mll1 also controls the intestinal stem cell genes Smoc2, Igfbp4, and Olfm4, which are induced in Wnt-mutated cancer cells but regulated by other signaling pathways such as Notch and NF-κB52,53." (PMID 33349639, 2020). "Expression levels of cancer stem cell (CSC) marker genes Lgr5, Smoc2, Axin2, Rnf43, and CD44 were markedly reduced in Prrc2a‐deficient tumors induced by AOM‐DSS treatment." (PMID 39582289, 2025). "Novel DNA methylation biomarkers for the prognosis during the early stages of cancer, such as INHBB, SMOC2, BDNF, and TBRG4, are being tested for clinical use to improve detection methods and guide the treatment and diagnoses of cancer patients." (PMID 34827720, 2021).
cancer (continued). "Calcitriol increases the expression of stemness-related genes, such as the leucine-rich repeat-containing G protein-coupled receptor 5 (LGR5), SMOC2, LRIG1, MEX3A, MSI1, and PTK7, attenuating the transformation into cancer stem cells, and, therefore, impacts tumorigenesis at a very early stage." (PMID 36364774, 2022). "After miR-519d inhibitor or SMOC2 overexpression plasmids were transfected into PANC-1 and BxPC-3 cells stably transduced with sh-circ0074298 or sh-NC, the CCK8 method was used to detect the proliferation ability of cancer cells." (PMID 34976169, 2022). "Secreted Protein Acidic and Rich in Cysteine (SPARC)-related modular calcium-binding protein-2 (SMOC2), a secreted matricellular protein, is reported to be involved in various processes related to cancer progression such as regulating the cell cycle, angiogenesis, and invasion." (PMID 32184420, 2020). "SMOC2 is a recently described non-structural component of the extracellular matrix (ECM) that is highly expressed during tissue remodeling processes with emerging roles in cancers, yet its role in RCC remains elusive." (PMID 35869056, 2022). "This may suggest that SMOC2 does not play a dominant role in regulation of cancer progression." (PMID 32884102, 2020).
cardiac diseases (2 papers, 2023 to 2025). "The Secreted modular calcium-binding protein 2 (SMOC2), a cysteine-rich acidic secreted protein, has been reported to link to cardiac diseases progression." (PMID 41304893, 2025).
infection (2 papers, 2021 to 2023). The state of being infected such as from the introduction of a foreign agent such as serum, vaccine, antigenic substance or organism. "Indeed, Bmp2 and Runx2 synergistically induced Smoc1 and Smoc2 expressions as an early response to infection." (PMID 34667264, 2021). "The mineralization assay showed that mineralized matrix nodules were readily detected in the BMP9-treated group on Day 14 after infection, and the mineralized nodules in the BMP9 combined with SMOC2-treated group were slightly increased compared with those in the group treated with BMP9 only." (PMID 36698376, 2023).
cardiovascular disease (1 paper, 2020). "SMOC2 rs13205533 has not been previously associated with cardiovascular disease related outcomes." (PMID 33171725, 2020).
SMOC2 also shares sentences with these, for which no sentence is quoted: diabetes (2 papers); Hepatic steatosis (2); metastatic cancer (2); Microdontia (2); rheumatoid arthritis (2); skeletal dysplasia (2); acute kidney injury (1); Alzheimer disease (1); Arrhythmia (1); arrhythmogenic right ventricular cardiomyopathy (1); autoimmune thyroid disease (1); chondrodysplasia (1); chronic pancreatitis (1); coronary artery disease (1); craniosynostosis (1); dilated cardiomyopathy (1); follicular adenomas (1); geographic atrophy (1); Graves disease (1); Hydrocephalus (1); Hyperkeratosis (1); hyperplastic polyp (1); hypertrophic cardiomyopathy (1); inflammation (1); inflammatory bowel disease (1); ischemia (1); kidney damage (1); kidney diseases (1); liver cancer (1); liver dysfunction (1).
A further 12 diseases each share a sentence with SMOC2 in 1 paper.